CHD4 (chromodomain helicase DNA binding protein 4)
Diseases named in the same sentence as CHD4 in open-access papers (continued):
Sharing a sentence is not in itself a finding about the gene and the disease.
cancer (continued). "CHD4 modulates therapeutic responses to DNA-damaging agents in BRCA mutant cancer cells." (PMID 34142021, 2021). "Furthermore, CHD4 expression reduction affects cancer cell’s autophagy process as well as the ERBB2 gene, which is an epithermal growth factor member, resulting in a drug resistance effect." (PMID 34142021, 2021). "Therefore, in cell lines from distinct cancer types, CHD4 silencing or ectopic PAD1/3 expression increased glycolysis and negatively impacted cell proliferation." (PMID 33741961, 2021). "CHD4 overexpression has been correlated with stemness and self-renewal of cancer stem cells." (PMID 33419089, 2021). "Although the potential therapeutic consequences and functions are yet to be determined, multiple genes associated with cancer or implied in non-hematologic malignancies were found as fusion partner genes in our dataset (e.g. CHD4, HOXA7, FOXO3)." (PMID 34340673, 2021). "However, CHD4 knockdown did not affect the expression of RAD51 or p21, the known targets of CHD4 in other cancer types that can modulate platinum sensitivity." (PMID 34161330, 2021). "Indeed, in the PANCAN study, CHD4 was identified as one of the 12 most important cancer-driving genes involved in chromatin epigenetics." (PMID 33981601, 2021). "In addition, our in vitro results indicated that CHD4 regulates cell growth, cancer stemness and epithelial-mesenchymal transition (EMT) in PTC cells." (PMID 33419089, 2021). "At the same time, the results of this study imply the cancer type-specific function of CHD4." (PMID 34161330, 2021). "CHD4 has been reported as an important regulator in several cancer types." (PMID 33994851, 2021). "Additionally, our study reveals a broad potential of CHD4 inhibition for cancer therapy and highlights chromatin remodelers as promising drug targets for cancer treatment." (PMID 32744500, 2020). "The relevance of CHD4 to cancer development and progression was substantiated by our study; when comparing the expression levels of CHD4 in paired tumor and tumor-adjacent tissues, we found that CHD4 was more highly expressed in tumor tissues than in the tumor-adjacent tissues." (PMID 32228507, 2020). "Therefore, our findings strongly suggest that CHD4 represents a promising new general target for cancer therapy, in agreement with its function as a regulator of SE activity." (PMID 32744500, 2020). "CHD4 is essential in the DDR and has been linked to various oncogenic effects, including inducing abnormal stem cell renewal, suppressed differentiation, and altered cell-cycle control, suggesting that CHD4 plays an essential role in cancer development." (PMID 32228507, 2020). "CHD4, which is highly expressed in cancer tissue, could be an independent prognostic factor for NSCLC patients." (PMID 32228507, 2020). "Our findings suggested that CHD4 could be a good therapeutic target to consider for cancer management." (PMID 32228507, 2020). "We hope that our work stimulates the development of a CHD4-specific inhibitor which would allow further studies regarding the biological activity of this chromatin remodeler and the future assessment of its potential as a new target for cancer therapy." (PMID 32744500, 2020). "In addition to its role in cancer progression, CHD4 plays essential roles in stem cell differentiation, embryonic development, striated muscle identity, and T cell and B cell development." (PMID 32577620, 2019). "CHD4 depletion has been shown to sensitize cancer cells to some chemotherapeutic agents." (PMID 32577620, 2019). "CHD4 expression also promotes resistance to chemotherapeutic agents in some cancers." (PMID 30872624, 2019). "As CHD4 frequently associates with DDR proteins to regulate transcription, drugs regulating the activity or the interactions of these proteins may be a more selective approach to inhibiting undesirable CHD4 functions in cancer cells." (PMID 32577620, 2019).
cancer (continued). "Also post-translational modification of CHD4 can modulate its function, which offers potentially additional drug targets for novel cancer therapies." (PMID 32577620, 2019). "In addition, the expression of CHD4 plays a dual role in sensitizing cancer cells to chemotherapeutic agents." (PMID 32577620, 2019). "Therefore, we used a Drosophila model for epithelial differentiation to assess the impact of cancer-derived dMi-2/CHD4 mutants in vivo." (PMID 29844320, 2018). "Compelling evidence indicates that CHD4 is a biomarker of drug sensitivity in cancer cells." (PMID 28055972, 2017). "Furthermore, global proteomic analysis of the NCI-60 cancer cell lines revealed that the CHD4 protein is the second most recurrent and significant protein associated with the sensitivity of 97 different drugs." (PMID 28055972, 2017). "Whereas a number of NuRD complex subunits have been implicated in cancer development, CHD4 has not emerged as a tumour suppressor from genetic analyses in humans or mice." (PMID 23697937, 2013). "However, it is still unknown how CHD4 plays a regulating role in B cell and T cell development during cancer progression." (PMID 40004553, 2025). "However, the signalling pathway by which CHD4 promotes cancer is still unclear." (PMID 36681835, 2023). "Emerging evidence indicates that CHD4 could be a potential therapeutic target for cancer therapy." (PMID 34161330, 2021). "Unfortunately, knockdown of CHD4 subunits can negatively affect the chromatin-remodeling ability of the NuRD complex, promoting cell proliferation, migration, and invasion, which represses apoptosis pathways and allows cancer cells to resist drugs that lead to DNA-damage." (PMID 34142021, 2021). "Moreover, our results showed that p-ERK expression levels were attenuated with the suppression of CHD4, leading us to speculate that CHD4 may play a role in cancer cell proliferation via activation of the MAPK/ERK signaling pathway." (PMID 32228507, 2020). "Thus, CHD4 may regulate cancer cell behavior through post-transcriptional modification, thereby regulating the sensitivity of cancer cells to various chemotherapeutic drugs." (PMID 31438571, 2019). "This suggests that CHD4 may affect cancer behavior and treatment responses to various cancers." (PMID 31438571, 2019). "More work is needed to characterize the synthetic lethal interaction between CHD4 and SETDB1 in TNBC and other cancers." (PMID 37970920, 2023). "CHD4, like UBE2N, is also involved in several cancer types and has been reported as essential for the maintenance of AML, and required for tumour cell survival in adult HGG." (PMID 37161535, 2023). "Recurrent P/LP variants were identified in individuals diagnosed with cancer from distinct families, in the following cancer genes: BRCA1 (n = 3), LZTR1 (n = 3), HNF1A (n = 2), CHEK2 (n = 2), MITF (n = 2), and CHD4 (n = 2)." (PMID 37377903, 2023). "Identifying a number of putative drivers, ARID1A, CHD4, HCFC1, STAG2, SMARCA4, and NCOR1 are known cancer driver genes." (PMID 37444571, 2023). "One can easily imagine that the mislocalization of CHD4 or reduced CHD4 concentrations as a result of a mutated or defective NLS in combination with remodeling activity losses could result in chromatin structure changes, which in turn could lead to the development of diseases such as cancer." (PMID 36861403, 2023). "In cancer cell lines, experimental CHD4 silencing and correlative expression over the CCLE both showed that CHD4 negatively regulated their expression." (PMID 33741961, 2021). "Here we show that CHD4 regulates expression of PADI1 (Protein Arginine Deiminase 1) and PADI3 in multiple cancer cell types modulating citrullination of arginine residues of the allosterically-regulated glycolytic enzyme pyruvate kinase M2 (PKM2)." (PMID 33741961, 2021). "Chromodomain-helicase-DNA-binding protein 4 (CHD4), a core subunit of the nucleosome remodeling and deacetylation (NuRD) complex is highly expressed in several cancers." (PMID 33419089, 2021).
cancer (continued). "High CHD4 expression positively correlated with HIF target genes and poor overall survivalCHD4 is a powerful candidate in the development of new anti-cancer agents in TNBC." (PMID 33981601, 2021). "Therefore, CHD4 may be serve as a potential target for the development of new anti-cancer agents." (PMID 32577620, 2019). "MCF10A cells were efficiently silenced for CHD4 and transduced cells plated for in vitro assays, as done for the corresponding MCF10DCIS.com cancer cells." (PMID 27779108, 2016). "Interestingly, in the context of its epigenetic role, studies have confirmed that CHD4 can interact with the methylation enzymes DNMT1, DNMT3B, EZH2 and G9a in cancer progression." (PMID 36681835, 2023). "The sensitivity to cisplatin did not significantly differ between CHD4 knockdown and control in these non-cancerous cell lines, which indicates the cancer specific involvement of CHD4 in the regulation of platinum sensitivity." (PMID 34161330, 2021). "Chromodomain helicase DNA-binding protein 4 (CHD4) has been shown to contribute to DNA repair and cell cycle promotion; however, its roles in cancer initiation and progression remain largely unknown." (PMID 32228507, 2020). "Compared with non-cancerous tissues, CHD4 was overexpressed in cancer tissues and CHD4 expression levels were closely related to clinical parameters of NSCLC patients." (PMID 32228507, 2020). "We showed that CHD4 depletion did not influence the proliferative, migratory and clonogenic potential of the non-transformed MCF10A cells, suggesting that CHD4 is selectively responsible of cell survival and proliferation in cancer cells only." (PMID 27779108, 2016). "Through gene set enrichment analysis (GSEA), we found that cancer-related pathways, including the TGF-beta signaling pathway, Wnt signaling pathway, mTOR signaling pathway, Hedgehog signaling pathway, and Notch signaling pathway, were enriched in TNBC with the CHD4-high phenotype." (PMID 38268032, 2024). "In addition, studies have found that patients with CHD4 deletion are sensitive to chemotherapy, but the deletion of CHD4 in BRCA2 mutant cells can enhance the resistance of cancer cells to cisplatin and PARP inhibitors by opening a channel known as “DNA damage tolerance”." (PMID 35548853, 2022). "At the same time, little evidence has shown alterations in CHD3 and CHD4 in human cancers." (PMID 35467222, 2022). "A major limitation of this study is that we could not assess whether CHD4 suppression actually sensitizes clinically chemo-resistant cancer to platinum agents." (PMID 34161330, 2021). "By contrast, in cancer tissues, 81 of 146 (55%) samples had weak or negative CHD4 expression, whereas 65 of 146 (45%) samples had moderate or strong CHD4 expression, demonstrating that the expression of CHD4 was higher in NSCLC tumor tissues than in adjacent non-cancerous tissues." (PMID 32228507, 2020). "The chromatin remodeling helicase CHD4, a component of the nucleosome remodeling and deacetylases (NuRD) complex, has been recently identified as an essential regulator of BC growth in murine and patient derived xenograft (PDX) BCs and correlates with poor prognosis in cancers." (PMID 30967373, 2019). "Silencing of CHD4 did not significantly reduce proliferation, migration ability and clonogenic potential, suggesting that depletion of CHD4 should be likely effective in a cancer-specific context without influencing the biological and cellular functions of normal tissues." (PMID 27779108, 2016).
cancer (continued). "There is a lack of clarity on whether CHD4 is utilized by specific transcription factors in diverse biological contexts of cancer progression, compelling the need for additional biochemistry and structural biology-related study on CHD4 to identify selective targets for therapeutic purposes." (PMID 40004553, 2025). "Although both CHD4 and EZH2 play roles in epigenetics, it has not been determined whether the two modifiers cooperate during cancer progression." (PMID 36681835, 2023).
tumor (63 papers, 2013 to 2026). "Tumor mutational data suggest frequent occurrence of multiple missense mutations in CHD4, which span across all regions of this gene." (PMID 40004553, 2025). "A high CHD4 expression is associated with a worse survival prognosis, a larger tumor size, resistance to drugs used in chemotherapy, and a lower migration rate without affecting tumor cell proliferation." (PMID 37761837, 2023). "CHD3 is a chromatin remodeler related to CHD4, which is implicated as a tumor suppressor in several female malignancies." (PMID 34142659, 2021). "The third transcript was associated with CHD2 and CHD4 genes, which play a critical role in tumor suppression, but also in cellular proliferation, senescence, and apoptosis." (PMID 32821278, 2020). "CHD4 expression was found to be associated with metastatic stage, tumor recurrence and survival status, and loss of CHD4 expression sensitizes cells to DNA-damaging agents." (PMID 32577620, 2019). "The catalytic core component of the NuRD complex CHD4 has been recently implicated in BC growth and suggested as a novel pharmacological target to block tumor progression." (PMID 30967373, 2019). "Metastasis-free survival (MeFS) was significantly associated with post-Tx tumor status (p = 0.0123), tumor regression grade (p = 0.0008), and CHD4 expression (p < 0.0001)." (PMID 31438571, 2019). "It implies that the phenotype of CHD4 deficiency in MSS cells is similar to MSI-H tumor response to IR." (PMID 31438571, 2019). "In our study, the high expression of CHD4 was significantly associated with advanced tumor depth of invasion, nodal metastasis, and increased vascular invasion, all representing aggressive behavior." (PMID 31438571, 2019). "In a triple negative BC cell line, CHD4 depletion causes a significant reduction of cell proliferation and migration in vitro and a dramatic decrease of the tumor mass in vivo." (PMID 30967373, 2019). "Loss of CHD4 in these genetic backgrounds would therefore engender chemo-resistance in what would otherwise be sensitive tumour cells." (PMID 30525090, 2018). "A recent paper has shown that CHD4 helps to maintain DNA hypermethylation-associated transcriptional silencing of tumor suppressor genes." (PMID 29467924, 2018). "In the CHD4 gene, tumor sample TCGA-C8-A27B had two missense mutations (P90Q and A235P), and TCGA-D8-A1JN had one missense mutation (I989F) and an X34 splice." (PMID 28055972, 2017). "Many chromatin remodeling gene mutations are necessary but not sufficient to drive endometrial tumorigenesis, suggesting that CHD4 may require an additional genetic alteration or activating mutation to promote tumor formation." (PMID 41417740, 2025). "Additionally, structural variants like deletions, amplifications, and fusions of CHD4 are found in different tumor types." (PMID 40004553, 2025). "Furthermore, high CHD4 mRNA expression in tumour tissue was significantly associated with poor overall survival (OS) (HR = 1.48; 95% CI 1.18–1.86; p < 0.0001)." (PMID 36681835, 2023). "Our results show that missense mutations (76%) predominate, so we suggest that the mutated CHD4 protein itself may contribute to tumor transformation via gain of function or dominant negative mechanisms." (PMID 33981601, 2021). "We therefore speculated that CHD4 might be a novel candidate tumor-associated gene in NSCLC." (PMID 32228507, 2020). "Epigenetic mechanisms involving CHD4 contribute to tumor development, cellular plasticity, and tumor heterogeneity." (PMID 40650308, 2025). "A similar inverse association was identified between CHD4 levels and the infiltration of CD8 + T cells and DCs, suggesting an adverse influence of CHD4 on tumor immunosurveillance." (PMID 39519018, 2024). "Considering that CHD4 expression was positively correlated with aggressive tumour behaviour, we further focused on DNMT3B and EZH2." (PMID 36681835, 2023). "CHD4 has oncogenic functions in initiating and maintaining epigenetic silencing of multiple tumor suppressor genes." (PMID 37974198, 2023).